TP53RK (TP53 regulating kinase)
Description:
Component of the EKC/KEOPS complex that is required for the formation of a threonylcarbamoyl group on adenosine at position 37 (t(6)A37) in tRNAs that read codons beginning with adenine. The complex is probably involved in the transfer of the threonylcarbamoyl moiety of threonylcarbamoyl-AMP (TC-AMP) to the N6 group of A37. TP53RK has ATPase activity in the context of the EKC/KEOPS complex and likely plays a supporting role to the catalytic subunit OSGEP (By similarity).
Synonyms: C20orf64; PRPK; dJ101A2.2; Nori-2p; BUD32; TPRKB; GAMOS4; Nori-2; dJ101A2
Tractability: Small molecule: a structure with a bound ligand is known; a high-quality ligand is known. PROTAC: ubiquitination databases record sites on it; its protein half-life has been measured; a small molecule that binds it is known.
Target class: Enzyme
Gene: Protein-coding gene on chromosome 20 (46,684,365 to 46,689,444, reverse strand). Ensembl gene ENSG00000172315.
Subcellular location: Cytoplasm; Nucleus
Pathways (Reactome):
Metabolism of RNA: tRNA modification in the nucleus and cytosol
Gene Ontology:
Molecular function: protein binding; protein serine kinase activity; protein serine/threonine kinase activity; ATP binding; catalytic activity; protein kinase activity
Biological process: protein phosphorylation; maintenance of translational fidelity; tRNA threonylcarbamoyladenosine metabolic process
Cellular component: cytoplasm; EKC/KEOPS complex; nucleus; cytosol; nucleoplasm
Genetic constraint (gnomAD): Loss-of-function variants: 17 observed, 13.88 expected, observed/expected ratio (o/e) 1.22, 90% interval 0.83 to 1.78. The upper end of that interval is the gene's LOEUF score, 1.78, which puts it in group 6 of 6, group 1 being the genes least tolerant of losing a copy. Missense variants: 343 observed, 308.85 expected, observed/expected ratio (o/e) 1.11, 90% interval 1.02 to 1.21. Synonymous variants: 131 observed, 128.05 expected, observed/expected ratio (o/e) 1.02, 90% interval 0.89 to 1.18.
Homologues: Orthologues: chimpanzee TP53RK (99% identical), macaque TP53RK (97% identical), dog TP53RK (92% identical), pig TP53RK (90% identical), guinea pig TP53RK (87% identical), rat Tp53rkb (84% identical), rat Tp53rka (83% identical), mouse Trp53rkb (83% identical), mouse Trp53rka (82% identical), tropical clawed frog tp53rk (65% identical), rabbit TP53RK (62% identical), zebrafish tp53rk (60% identical), and 2 more.
Diseases named in the same sentence as TP53RK in open-access papers:
TP53RK is named in the same sentence as 35 diseases in open-access papers, as found by Europe PMC text mining. Sharing a sentence is not in itself a finding about the gene and the disease. The quoted sentences say what the papers report.
Galloway-Mowat syndrome (9 papers, 2018 to 2023). Galloway syndrome is characterized by the association of nephrotic syndrome and central nervous system anomalies. "One familial case of Galloway-Mowat syndrome [MIM: 617730] due to a novel TP53RK [MIM: 608679] mutation, a gene within 500 kb of rs3091552, also showed a cleft palate." (PMID 33692830, 2021). "Loss-of-function mutations in OSGEP, TP53RK, TPRKN or LAGE3, which encode the four subunits of the KEOPS complex (Kinase, Endopeptidase and Other Protein of small Size) result in Galloway-Mowat syndrome (GAMOS, #MIM251300), an early-onset nephrotic disorder with severe PM." (PMID 31832602, 2019). "Galloway-Mowat syndrome (GAMOS) is a group of rare hereditary diseases by the combination of early onset steroid-resistant nephrotic syndrome (SRNS) and microcephaly with brain anomalies caused by WDR73, LAGE3, OSGEP, TP53RK, TPRKB, GON7, WDR4 or NUP133 mutations." (PMID 36755238, 2023). "The term “Galloway-Mowat syndrome 1 (GAMOS1)” is now used for GAMOS caused by mutations in WDR73, and “Galloway-Mowat syndrome 2-5 (GAMOS2-5)” is used for GAMOS with mutations in LAGE3, OSGEP, TP53RK, and TPRKB, respectively." (PMID 30558655, 2018). "For example, mutations in OSGEP, TP53RK, TPRKB, LAGE3 and C14orf142, encoding all five subunits of the human cytoplasmic KEOPS complex, lead to defective t6A modification and Galloway-Mowat syndrome (GAMOS), characterised by early-onset nephrotic syndrome, microcephaly and brain anomalies." (PMID 32047918, 2020). "We recently identified autosomal recessive mutations in genes encoding four of the five subunits of human KEOPS complex, namely LAGE3, OSGEP, TP53RK, and TPRKB in patients with Galloway-Mowat syndrome (GAMOS, OMIM#251300)." (PMID 31481669, 2019).
multiple myeloma (6 papers, 2020 to 2026). "One study identified EYA2 as a potential target for molecular therapy in a subtype of acute myeloid leukemia, whereas OCSTAMP mRNA levels were connected to multiple myeloma and TP53RK expression is inversely correlated with multiple myeloma survival." (PMID 38601075, 2024). "TP53RK has been linked with colorectal cancer metastasis and identified as a target for multiple myeloma and enitociclib may provide an opportunity to target TP53RK." (PMID 37882668, 2023). "Studies have shown that TP53RK is becoming a potential novel target in multiple myeloma." (PMID 35433409, 2022).
nephrotic syndrome (6 papers, 2016 to 2025). A collection of symptoms that include severe edema, proteinuria, and hypoalbuminemia; it is indicative of renal dysfunction. "The clinical characteristics of the three children with TP53RK mutations are significantly different from the known GAMOS4 traits, including early nephrotic syndrome and mortality mainly occurring in the first year of life." (PMID 36873107, 2023). "Galloway–Mowat syndrome-4 caused by the TP53RK gene is mainly characterized by microcephaly, nephrotic syndrome, and severe central nervous system abnormalities (severe global developmental delay, cerebral atrophy, visual impairment, and dystonia)." (PMID 36873107, 2023). "It has been reported that OSGEP and TP53RK, both of which are implicated in nephrotic syndrome with primary microcephaly, interact with components of the ARP2/3 complex including ARPC1B involved in actin remodeling at lamellipodia." (PMID 29333229, 2016). "An in vivo study recently showed that knockdown of OSGEP and TP53RK resulted in defects in the actin cytoskeleton and a decrease of human podocyte migration rate; these findings are compatible with the pathological manifestation in the development of nephrotic syndrome." (PMID 30558655, 2018).
chronic kidney disease (1 paper, 2023). Impairment of the renal function secondary to chronic kidney damage persisting for three or more months. "Tumor protein 53 regulating kinase (TP53RK) is positively correlated to renal dysfunction and fibrosis in chronic kidney disease (CKD)." (PMID 37382161, 2023).
fibrosis (1 paper, 2023). the formation of excess fibrous connective tissue in an organ or tissue in a reparative or reactive process. "As expected, TP53RK knockdown in mice remarkably alleviated tubule injury and tubulointerstitial fibrosis in UUO kidneys." (PMID 37382161, 2023).
narcolepsy (1 paper, 2015). A sleep disorder characterized by a tendency for excessive sleepiness during the day which occurs even after adequate sleep in the nighttime.
osteosarcoma (1 paper, 2020). A usually aggressive malignant bone-forming mesenchymal neoplasm, predominantly affecting adolescents and young adults. "We further validated that TRRAP, PKMYT1, and TP53RK are required for osteosarcoma cell proliferation and colony formation." (PMID 32944406, 2020). "Among these targets, we analyzed 3 kinases, TRRAP, PKMYT1, and TP53RK, to validate their oncogenic functions in osteosarcoma." (PMID 32944406, 2020). "Consequently, we decided to validate whether the 3 other hits from our screening, TRRAP, PKMYT1, and TP53RK, were truly essential in osteosarcoma cell lines, given that their functions in osteosarcoma remain unknown." (PMID 32944406, 2020).
renal fibrosis (1 paper, 2023). A final common manifestation of a wide variety of chronic kidney diseases characterized by glomerulosclerosis and tubulointerstitial fibrosis. "Taken together, TP53RK expression is significantly upregulated both at the transcriptional and protein levels in fibrotic kidneys, and it is associated with the extent of renal fibrosis and kidney function impairment." (PMID 37382161, 2023). "In this study, the role of tumor protein 53 regulating kinase (TP53RK) in the pathogenesis of renal fibrosis and its underlying mechanisms is investigated." (PMID 37382161, 2023). "The TP53RK protein levels showed positive correlation with renal fibrosis scores, blood urea nitrogen (BUN) levels, and serum creatinine (sCr) levels, and showed negative correlation with estimated glomerular filtration rate (eGFR)." (PMID 37382161, 2023). "Second, it would be better to generate renal tubular and fibroblast specific Birc5 knockout mice to fully demonstrate the function of Birc5 as the downstream signaling of TP53RK in renal fibrosis." (PMID 37382161, 2023). "The data above led us to investigate the therapeutic potential of retarding renal fibrosis by targeting TP53RK/Birc5 axis." (PMID 37382161, 2023). "Interestingly, specific deletion of TP53RK either in renal tubule or in fibroblasts in mice can mitigate renal fibrosis in CKD models." (PMID 37382161, 2023). "Specific genetic deletion of TP53RK either in renal tubules or in fibroblasts could mitigate renal fibrosis in mice models." (PMID 37382161, 2023). "Especially noteworthy is that targeting the TP53RK/Birc5 axis to retard renal fibrosis is of high translational probability, because the TP53RK inhibitor FA is a clinically commonly used antibiotic and Birc5 selective inhibitor YM‐155 is currently in clinical phase 2 trials." (PMID 37382161, 2023). "Deleting TP53RK in renal tubule or fibroblasts mitigates renal fibrosis." (PMID 37382161, 2023). "In this study, we demonstrated that TP53RK, an atypical protein kinase and an important component of the EKC/KEOPS complex, contributed critically to the pathogenesis of renal fibrosis." (PMID 37382161, 2023). "TP53RK was upregulated in kidneys of CKD patients and renal fibrosis murine models induced by UUO and UIR." (PMID 37382161, 2023).
schizophrenia (1 paper, 2024). A major psychotic disorder characterized by abnormalities in the perception or expression of reality.
tuberculosis (1 paper, 2024). A chronic, recurrent infection caused by the bacterium Mycobacterium tuberculosis. "Interestingly, TP53RK was significantly downregulated in healthy Holstein cattle, compared to those PCR-positive for bovine tuberculosis, and was expressed at significantly lower levels in foot and mouth disease virus carriers than non-carriers." (PMID 38601075, 2024).
cancer (10 papers, 2008 to 2026). A tumor composed of atypical neoplastic, often pleomorphic cells that invade other tissues. "Both PHF23 and TP53RK mRNA downregulation was confirmed by RNA-seq analysis in the blood of enitociclib-treated patients and further studies are warranted to uncover the utility of enitociclib to downregulate these potential cancer targets." (PMID 37882668, 2023).
tumor (8 papers, 2018 to 2026). "So even though both groups of C-type cells have similar genomic mutation patterns, only cells that highly expressed TP53RK and TPRKB successfully metastasized to lymph node, which indicated that EKC/KEOPS complex may be beneficial for tumor metastasis." (PMID 35974387, 2022).
kidney diseases (1 paper, 2019). "Variant analyses of patients 1 and 2 were performed by targeted massive parallel sequencing using an updated version of our kidney disease gene panel that includes more than 200 genes causative of or associated with inherited kidney diseases (including WDR73, TPRKB, TP53RK, LARGE3, and OSGEP genes)." (PMID 30975089, 2019).
neurodevelopmental disorder (1 paper, 2023). A behavioral and cognitive disorder with onset during the developmental period that involves impaired or aberrant development of intellectual, motor, or social functions. "In conclusion, four novel TP53RK variants were identified in three unrelated neurodevelopmental disorder patients using WES." (PMID 36873107, 2023).
TP53RK also shares sentences with these, for which no sentence is quoted: colon cancer (5 papers); colorectal cancer (3); microcephaly (3); skin cancer (3); colon adenocarcinoma (2); cutaneous squamous cell carcinoma (2); Primary microcephaly (2); acute kidney injury (1); acute myeloid leukemia (1); atherosclerosis (1); blood cancers (1); brain disorder (1); breast carcinoma (1); Cerebral atrophy (1); cryptococcosis (1); developmental delay (1); Dystonia (1); fungal meningitis (1); hepatocellular carcinoma (1); lung carcinoma (1); myeloid leukemia (1).